BRCA2 (BRCA2 DNA repair associated)
Diseases named in the same sentence as BRCA2 in open-access papers (continued):
Sharing a sentence is not in itself a finding about the gene and the disease.
melanoma (126 papers, 2005 to 2026). A malignant, usually aggressive tumor composed of atypical, neoplastic melanocytes. "Genetic mutations in KRAS, NRAS, and BRAF were commonly implicated in the development of both melanoma and CRC, while mutations in CDKN2A and BRCA2 were specifically significant in melanoma." (PMID 40447784, 2025). "Melanoma is generally immune cold, and predictors of anti–PD-1 response include BRCA2 mutations and the IPRES transcriptional signature, rather than mutation burden." (PMID 41148213, 2025). "No genomic alterations were revealed in either dormant or parental melanoma cells for 18 commonly mutated genes including oncogenes or tumour suppressor genes such as Pten, Brca2, or Pml." (PMID 39223638, 2024). "Although studies assessing the association between melanoma and BRCA are restricted and often inconclusive, BRCA2 mutation carriers have been shown to have an increased risk of melanoma." (PMID 38974244, 2024). "We estimated a hazard ratio of 9.90 for a second diagnosis of melanoma after initial diagnosis in BRCA2 mutation carriers and 11.4 for those with a BRCA1 mutation." (PMID 38741145, 2024). "During the mean follow-up period of eight years, 3.7% of women with a BRCA1 mutation (133 of 3,623) and 3.8% of women with a BRCA2 mutation (99 of 2,584) reported a diagnosis of skin cancer (including both keratinocyte carcinomas and melanoma)." (PMID 38741145, 2024). "BRCA1 and BRCA2 pathogenic variants (PVs) are associated with significantly increased lifetime risks of cancers of the breast, ovary, pancreas, prostate, and melanoma." (PMID 39001386, 2024). "As recently highlighted by Li and colleagues, our analysis showed a very weak association between melanoma risk and germline BRCA2 alterations (only one individual out of 98 patients)." (PMID 38974244, 2024). "According to NCCN (2023), studies investigating BRCA2 P/LP variants and melanoma showed some evidence of an association, even though inconsistent conclusions have been drawn." (PMID 37347260, 2023). "An aggressive form of skin cancer (melanoma) is also more common amongst people who have BRCA2 mutations." (PMID 36010323, 2022). "The tumor spectrum of cancers associated with pathogenic mutations in BRCA2 include: breast, ovarian, fallopian tube, melanoma, prostate, pancreatic, and lung cancers." (PMID 34065235, 2021). "Pathogenic variants in many other genes (including c-kit, MAGE-1, CDK4, BAP1, and BRCA2) have also been associated with melanoma." (PMID 33509032, 2021). "Although it remains a controversial issue, several studies have shown an increased prevalence of melanoma also among BRCA2 mutation carriers." (PMID 34660619, 2021). "Germline mutations of BRCA1 and BRCA2 are significantly associated with the development of multiple neoplasms, including breast, ovarian, stomach, pancreas, colon, and melanoma." (PMID 32493233, 2020). "Literature suggests a possible association between germline BRCA2 pathogenic variants and an elevated risk for melanoma." (PMID 32655641, 2020). "That said, on balance, it seems unlikely that germline BRCA1 or BRCA2 variants profoundly contribute to any melanoma subtype." (PMID 31610093, 2020). "For several decades, the role of germline BRCA1/BRCA2 variants in predisposition to melanoma has been controversial." (PMID 31610093, 2020). "Examples are mutations in the DNA repair gene BRCA2 in melanoma or in different stage IV cancers alterations in NOTCH, TERT, and NF1." (PMID 33353145, 2020). "It is interesting that the somatic mutation load of BRCA2 in normal tissue was significantly lower than that in the tumors both in this study and the other two groups of melanoma patients." (PMID 32359357, 2020). "BRCA2 deleterious mutations confer a similar risk of breast and ovarian cancer, as well as pancreatic cancer, prostate cancer, stomach cancer, and melanoma as well." (PMID 32493233, 2020).
melanoma (continued). "The risk of uveal melanoma (a rare type of melanoma) has been reported to be higher in BRCA2 mutation carriers." (PMID 29433453, 2018). "In contrast to BRCA1, many studies have suggested an association between BRCA2 mutations and melanoma." (PMID 30286154, 2018). "We have previously reported the significantly higher prevalence of the BRCA2 N991D variant in melanoma patients when compared to control subjects (OR = 1.8, p = 0.002), in contrast to T1915M and N372H variants." (PMID 30286154, 2018). "Somatic BRCA2 mutations have been found e.g. in melanoma, where these mutations have been found to correlate with anti-PD-1 responsiveness." (PMID 29522538, 2018). "The most commonly reported cancers with BRCA2 mutations include breast, pancreas, prostate, and melanoma." (PMID 30286154, 2018). "In contrast, suspected BRCA2 mutation carriers have shown an increased risk (2-5 times) of developing melanoma compared with the general population." (PMID 27776349, 2017). "The PALB2/BRCA2 protein interaction, as well as the increased melanoma risk observed in families harbouring BRCA2 mutations, makes PALB2 a candidate for melanoma susceptibility." (PMID 24949998, 2014). "Malignant melanoma, both cutaneous and ocular, has been reported in BRCA2 families, and an excess risk has been reported in the BRCA2-BCLC families." (PMID 17213823, 2007). "Moreover, dermatological surveillance has emerged as a formal recommendation in patients with known germline variants, such as BRCA1 and BRCA2 carriers, with an increased risk for melanoma." (PMID 40649916, 2025). "Malignant melanoma has been reported also in BRCA2‐mutated families." (PMID 39609109, 2025). "BRCA2 PVs may also increase the risk for other cancers, including uterine cancer, leukemia, melanoma, and esophagus cancer, though evidence remains inconclusive." (PMID 40462315, 2025). "Melanoma risk estimates of 3–5% and 2–6% for BRCA2 were provided by two websites." (PMID 39001386, 2024). "Additionally, the germline variants in BRCA2 have been found to increase the risk of melanoma and affect survival rates." (PMID 39795882, 2024). "Regarding the incidence of cutaneous malignancies, we diagnosed an in situ melanoma in only one patient with a BRCA2 mutation, while another BRCA2 mutation carrier reported a positive familiar history for melanoma in his sister, that died due to melanoma, carryingBRCA2 mutation too." (PMID 35573021, 2022). "Research evaluating the association between BRCA1/2 mutations and skin cancers is limited; indeed, while no studies showed a statistically significant association between BRCA1 mutations and melanoma, the surveys investigating BRCA2 mutations and melanoma produced inconsistent conclusions." (PMID 35573021, 2022). "A few studies suggest that melanoma risk, both cutaneous and ocular, may be elevated in some families with BRCA2 carriers." (PMID 34356066, 2021). "In the same way, analyses of familial melanoma cohorts have reported germline pathogenic alleles of BRCA2 providing some evidence that germline variants in these genes might contribute to disease pathogenesis—but do they?" (PMID 31610093, 2020). "By “pooling” all subtypes together in this way it is possible that any statistical signal that might link BRCA1 or BRCA2 variants to rarer melanoma subtypes could be diluted." (PMID 31610093, 2020). "Moreover, the BRCA2 mutations carriers have greater risk of bile duct, gall bladder, pancreatic, gastro-intestinal tumors, and melanoma, while the BRCA1 mutations carriers of CC." (PMID 33287145, 2020). "We found that several HRR-associated genes, including DDB2, RAD51, BRCA1, XRCC2 and BRCA2, are overexpressed in melanoma cells compared to primary melanocyte cultures, while the expression of the NER-associated genes XPA, ERCC1 and ERCC4 showed no clear differences." (PMID 32719412, 2020). "Consistently our results point at the rarity of BRCA2 mutations among Polish melanoma patients." (PMID 30286154, 2018).
melanoma (continued). "Furthermore, the possible involvement of homologous recombination (HR) repair has been suggested recently; specifically, enrichment of mutations in BRCA2, an HR factor, has been identified in melanomas responsive to anti-PD-1 therapy." (PMID 29170499, 2017). "A plausible candidate that might contribute to the melanoma risk landscape in certain individuals is partner and localizer of BRCA2 (PALB2)." (PMID 24949998, 2014). "Moreover, carriers of mutations in BRCA2 - the BC predisposition gene - have an increased risk of melanoma, while carriers of mutations in the melanoma susceptibility gene - CDKN2A - exhibit a higher than expected risk of BC." (PMID 25077705, 2014). "Overall, seven (14.6%) melanoma families had a detectable mutation in p16CDKN2A or BRCA2 gene." (PMID 19799798, 2009). "A significant association between BRCA2 and excess melanoma has also been reported." (PMID 16884528, 2006). "Additionally, previous studies reported that other genes are frequently mutated in melanoma and other cancer types, including BRCA2 (9/112, 8%), LRP1B (9/112, 8%), MET (8/112, 7%), PRKDC (7/112, 6%), NOTCH4 (7/112, 6%), CCND3 (6/112, 5%), and FGF3/4/19 (6/112, 5%)." (PMID 37649078, 2023). "In support of the hypothesis that the genomic instability of HR-d tumors results in increased immunogenicity, a retrospective study of melanoma patients treated with ICI therapy found that tumors that regressed were enriched for BRCA2 loss of function mutations and harbored a higher TMB." (PMID 35547873, 2022). "In this respect, a transcriptomic study in biopsies of pretreated melanoma revealed that the mutational loads improved survival independently from the capacity to respond to immunotherapy, whereas responder patients were characterized by an enrichment for mutations in the DNA repair gene BRCA2." (PMID 34207514, 2021). "In addition, BRCA2 mutations are enriched in melanomas responsive to anti-PD-1." (PMID 29170499, 2017). "While there is evidence for melanoma development, there appear to be mixed findings for BRCA2 involvement in CRC, with further research being needed to confirm either stance." (PMID 40447784, 2025). "In contrast, RAS pathway mutant melanoma cells frequently rely on RAS pathway signaling to facilitate DNA repair by driving gene expression of major DNA repair factors such as BRCA2, BRIP1/FANCJ, and XRCC5." (PMID 40560846, 2025). "Several published studies reported a positive association between BRCA2 and non‐HBOC cancers, including melanoma, stomach, esophagus, uterine, endometrial, and leukemia." (PMID 40462315, 2025). "Other high- and moderate-penetrance genes—such as BAP1, POT1, BRCA2, and TERT—were also included, reflecting an expanded institutional approach to hereditary melanoma risk assessment." (PMID 40863406, 2025). "Genetic mutations in KRAS, NRAS, and BRAF were frequently observed in both melanoma and CRC, whereas BRCA2 and CDKN2A mutations were specific to melanoma." (PMID 40447784, 2025). "The BRCA2 variant named c.4284dup (p.Gln1429fs) has been observed in both melanoma and MBC, whereas another BRCA2 variant named c.7681C>T (p.Gln2561Ter) was present in one individual with MBC and one with PC." (PMID 38974244, 2024). "The germline variants of BRCA2, POLE, WRN, FANCI, PALB2, and RAD54B genes, involved in DNS repair mechanisms, have been implicated in rendering melanoma patients more susceptible to tumor progression and affecting their response to treatments." (PMID 39795882, 2024). "We estimated the cumulative risk of melanoma between age 20 and 80 years to be 2.5% for women who carry BRCA1 mutations and 2.3% for women who carry BRCA2 mutations." (PMID 38741145, 2024). "Between age 40 and 79 the annual risk for melanoma was 0.09% for BRCA1 carriers (90/100,000 per year) and 0.12% for BRCA2 carriers (120 per 100,000 per year)." (PMID 38741145, 2024).
melanoma (continued). "The cumulative risk of melanoma was 2.5% for BRCA1 carriers and 2.3% for BRCA2 carriers, compared to 1.5% for women in the general population in the United States." (PMID 38741145, 2024). "PALB2 protein partners with BRCA2 in homologous recombination, and mutations in PALB2 are similarly implicated in an increased melanoma risk and poorer survival." (PMID 39795882, 2024). "The lifetime risk of melanoma was approximately 2.5% for women who carried BRCA1 mutations and 2.1% for women who carried BRCA2 mutations, compared to 1.5% for white women in the general population in the United States." (PMID 38741145, 2024). "We found the risk for melanoma in BRCA1 and BRCA2 mutation carriers to be only slightly higher than expected, based on US population rates." (PMID 38741145, 2024). "As regards the individuals with melanoma, only one out of 98 analyzed patients was carrier of a germline BRCA2 PV, showing a family history of female BC in two first-degree relatives (mother and sister)." (PMID 38974244, 2024). "Two patients with monoallelic somatic gene loss also had responses, one with a BRCA1 alteration (HNSCC) and one with a BRCA2 alteration (melanoma)." (PMID 37277454, 2023). "Altogether, 7/11 double mutation carriers (excluded from the analysis of clinicopathological data) carried at least one mutation in high-risk melanoma (POT1/CHEK2) or syndromic (ATM/WRN, BRCA1, BRCA2 (2x), CHEK2/RAD51D, NBN) genes." (PMID 33050356, 2020). "We have shown an overexpression of RAD51 and other HRR genes, DDB2, XRCC2, BRCA1 and BRCA2, in melanoma cell lines and this has a protective role against DNA damage accumulation after genotoxic stress." (PMID 32719412, 2020). "The low-risk melanoma gene group revealed 12 carriers of mutations in 5 genes (another TYRP1 carrier also had a pathogenic BRCA2 mutation)." (PMID 33050356, 2020). "They advise considering annual skin and eye examination as screening for melanoma in all BRCA2 carriers." (PMID 32655641, 2020). "New loci included common variants in BRCA2 (distinct to known rare high penetrance cancer risk variants), and in CTLA4, a target of immunotherapy in melanoma." (PMID 31174203, 2019). "The sequence analysis performed on the proband paraffin-embedded melanoma samples revealed the presence of the two BRCA1 and BRCA2 variants and a novel BRCA2 c.4297G>A somatic variant (p.Gly1433Arg)." (PMID 29346284, 2018). "The MM lesion carried a BRAFV600E and a TERT promoter mutation.As the family story was consistent with a genetic predisposition to cancer, we performed mutational analysis of genes involved in familial melanoma and CLL, and of BRCA1 and BRCA2." (PMID 29371889, 2018). "It strongly suggests that this BRCA2 variant is pathogenic, and carriers of this change are at an increased risk of BRCA-related cancers, that include breast, prostate and melanoma." (PMID 30286154, 2018). "Transcripts associated with BRCA1, BRCA2, ATM and CHEK2 showed altered expression in melanoma cell lines after cisplatin treatment." (PMID 23940574, 2013). "Several low-penetrance candidate genes, such as breast cancer susceptibilitygene 2 (BRCA2) and melanocortin-1-receptor (MC1R), have been also implicated in melanoma predisposition." (PMID 19799798, 2009).
melanoma (continued). "While there is limited research on the germline mutations of the BRCA2 gene in melanoma, there is no information available regarding somatic variations." (PMID 41142596, 2025). "Gained therapies included tyrosine kinase inhibitors (TKIs) in the context of EGFR-mutated NSCLC, trastuzumab deruxtecan for ERBB2-mutated NSCLC, ivosidenib for IDH1-mutated CCA, MEK and RAF inhibitor combination therapies for BRAF V600E melanomas, and PARP inhibitors for BRCA2-mutated HGSOC." (PMID 40399445, 2025). "Unlike ovarian, breast, pancreatic, and prostate cancer, melanoma has a much lower frequency of BRCA1 and BRCA2 mutations, and there is little evidence of its contribution to melanoma pathogenesis." (PMID 40842586, 2025). "Regarding the presently detected variants of pathogenic significance, melanoma was among the top 6 most common cancers to exhibit mutations in each of those genes (except BRCA2), which were not reported with significant frequency in rhabdomyosarcoma." (PMID 40090763, 2025). "It has not been clearly established if skin cancer or melanoma are manifestations of BRCA1 or BRCA2 mutation carrier status." (PMID 38741145, 2024). "Additionally, melanoma risk is increased in mixed cancer syndromes caused by mutations in PTEN, BRCA2, BRCA1, RB1 and TP5330." (PMID 36805510, 2023). "Certain genetic mutations in melanoma, including JAK1, JAK2, B2M and PTEN, etc., correlate with negative treatment response of PD-1 blockade therapy, while BRCA2 mutations were reported enriched in melanomas responsive to this treatment." (PMID 32333081, 2020). "We have confirmed the regulation of four exemplary genes, namely RAD51, BRCA1, BRCA2, and XRCC2 by vemurafenib treatment in further BRAF-mutated melanoma cell lines using RT-qPCR analysis at the mRNA level and the regulation of Rad51 at protein level using immunoblot analysis." (PMID 32719412, 2020). "It should be noted that large‐scale studies of this type cannot conclude that BRCA1 or BRCA2 variants never contribute to melanoma formation, just that at a population level they are not major contributors to the burden of disease." (PMID 31610093, 2020). "Suspected BRCA2 carriers have shown an increased melanoma risk in the majority (but not all) of reports." (PMID 30286154, 2018). "Finally, we would like to focus the melanoma found in our patient, in which next-generation sequencing (NGS) detected a somatic BRCA2 variant c.4297G>A (p.Gly1433Arg) reported as pathogenic by the COSMIC database." (PMID 29346284, 2018). "Moreover, confocal microscopy analyses determined LOXL3 and BRCA2 co-localization in the cytoplasm and perinuclear area of melanoma cells." (PMID 29229995, 2018). "An earlier study by the Breast Linkage Consortium reported an increased incidence of gallbladder, bile duct, stomach cancer, and malignant melanoma in BRCA2-mutation carriers, yet recent evidence has not substantiated this association." (PMID 22312502, 2011). "Cases with either familial or sporadic melanoma originating from other areas of the Sardinia island presented no germline mutation in BRCA2 gene." (PMID 19799798, 2009). "For melanoma susceptibility, investigations at germline level indicated that p16CDKN2A was exclusively mutated in 16/545 (2.9%) non-Sardinian patients, whereas BRCA2 germline mutations were observed in 4/91 (4.4%) patients from North Sardinia only." (PMID 19799798, 2009). "Here, our aim was to investigate whether patients in the Hungarian melanoma cohort (n = 17) with increased risk carry any pathogenic or likely pathogenic germline variants of the BRCA2, POLE, WRN, FANCI, PALB2, and RAD54B genes associated with melanoma survival and response to therapy." (PMID 39795882, 2024).